MTOR (mechanistic target of rapamycin kinase)
Diseases named in the same sentence as MTOR in open-access papers (continued):
Sharing a sentence is not in itself a finding about the gene and the disease.
glioma (continued). "As it turned out, the inhibitors of this protein were also not cytotoxic in the single application; however, when combined with mTOR inhibitors, they significantly increased their effectiveness in eliminating gliomas." (PMID 33171577, 2020). "Previous experiments have determined that ARG inhibited glioma cells through the AKT/mTOR-mediated autophagy." (PMID 33015162, 2020). "In our present study, the inhibitory effects of celastrol on VM formation, angiogenesis, and the related PI3K/Akt/mTOR signaling pathway were investigated in a model of U87 glioma orthotopic xenografts and in U87 and U251 cells." (PMID 32116702, 2020). "Nevertheless, we further should investigate how the cytoplasmic mTOR senses the nucleus JMJD2A signal in glioma." (PMID 32256210, 2020). "It was shown that the treatment of glioma cells with swainsonine hinders cell proliferation, migration, and invasion via downregulating miR-92a levels and Akt/mTOR activities." (PMID 33066509, 2020). "The characteristic mTOR inhibitor (mTORI) sensitivity of high-grade glioma cell lines has been studied previously." (PMID 31187466, 2020). "Collectively, these results demonstrated that knockdown of CBX3 reversed LINC00998 overexpression-mediated suppression of malignant phenotypes of glioma cells and Akt/mTOR signaling pathway key protein phosphorylation levels." (PMID 33268783, 2020). "Dual PI3Kα and mTOR inhibition potently disrupted glioma stem cell frequencies in all GSC lines tested." (PMID 33318517, 2020). "LncRNA CRNDE can promote the growth and invasion of glioma cells through the mammalian target of rapamycin (mTOR) signaling pathway." (PMID 32934196, 2020). "In glioma cells, the activation of polyamine catabolism alters the location of mTOR, negatively affecting mTOR-mediated protein synthesis and leading to apoptosis." (PMID 33292222, 2020). "To elucidate the underlying mechanism of this action, we investigated the AKT/mTOR pathway, the well-known pathway which regulates autophagy and also plays a key role in cell survival/death of gliomas." (PMID 31936835, 2020). "In this research, we demonstrated that ARG mediated the anticancer properties of autophagy by targeting the AKT/mTOR pathway in glioma cells." (PMID 33015162, 2020). "Collectively, XL388 efficiently inhibits human glioma cell growth, through Akt-mTOR-dependent and -independent mechanisms." (PMID 33159013, 2020). "The role of mTOR is fully understood in adult glioma, and a recent study demonstrated that activation of mTORC1/mTORC2 signaling in pediatric low-grade glioma." (PMID 32256210, 2020). "We reveal that AEBP1 exerts its tumor-promoting effects by mainly activating mTOR pathway in Glioma." (PMID 32938364, 2020). "Later, a study revealed that ARL4D expression in gliomas is dependent on the loss of PTEN tumor suppressor and consequent activation of the Akt/mammalian Target of Rapamycin (mTOR) pathway." (PMID 32426352, 2020). "Taken together, JMJD2A regulates the activation of the Akt-mTOR pathway and protein synthesis in human glioma cells." (PMID 32256210, 2020). "The PI3K/Akt/mTOR signaling pathway is over activated in glioma tissues, and this increased activation is closely related to malignancy and chemoresistance of gliomas." (PMID 33221748, 2020). "Collectively, lncRNA MEG3 decreased the phosphorylation levels of PI3K/AKT/mTOR pathways by enhancing Sirt7 and finally activates autophagy and improves the prognosis of glioma." (PMID 33029125, 2020). "Hypoxia induces a positive regulation of MCT-1, while a deletion of MCT-1 decreases glycolysis and metabolism rates in glioma cells through by regulating the mTOR signaling pathway, affecting tumor proliferation, migration, and invasion." (PMID 32707662, 2020). "Taken together, our findings indicate that the inhibition of VM formation by celastrol is in part due to suppression of PI3K/Akt/mTOR signaling in glioma cells." (PMID 32116702, 2020).
glioma (continued). "MiR-450a-5p exhibited a negative correlation with the EGFR via targeting the 3′UTR of EGFR, and regulated the EGFR-induced PI3K/AKT/mTOR signaling pathway in glioma cells." (PMID 32820249, 2020). "The combination therapy of CDK4/CDK6 and mTOR inhibitors resulted in the synergistic growth arrest of diffuse bridge glioma cells." (PMID 32508030, 2020). "Because previous conclusions on the PI3K pathway in glioma were primarily restricted to the scope of PI3K kinases, PTEN, and mTOR mutations, we sought to elaborate on other PI3K pathway genes." (PMID 33747896, 2020). "It is known that one of the major biological changes in glioma is the alteration of the PI3K (phosphatidyl inositol 3 kinase)/AKT/mTOR pathway." (PMID 32093151, 2020). "And last, we analyze the relationship between AEBP1 and key proteins to identify that AEBP1 exerts its tumor-promoting effects by mainly activating mTOR pathway in Glioma." (PMID 32938364, 2020). "Here we first show that mTOR was also activated in glioma and that JMJD2A was an upstream driver of the mTOR pathway." (PMID 32256210, 2020). "We found that the Akt-mTOR pathway is hyperactivated in glioma tissues, where the expression of JMJD2A was also high, indicating that JMJD2A is related to mTOR activation." (PMID 32256210, 2020). "As human gliomas represent another mTOR pathway-activated cancer type arising from its frequent occurrence of EGFRvIII and/or loss of tumor suppressor PTEN, we also examined TF expression in these tumors." (PMID 32923403, 2020). "Overactivation of Akt-mTOR cascade is frequently detected in human glioma, promoting tumor cell survival, growth, proliferation, motility, angiogenesis and apoptosis-resistance." (PMID 33159013, 2020). "The results showed that rapamycin-mediated mTOR inhibition reduced the protein synthesis in glioma cell U87MG and blocked the effect of JMJD2A overexpression on protein synthesis." (PMID 32256210, 2020). "NLGN3 was also found to stimulate FAK upstream of PI3K/mTOR and increased synapse-related genes in the glioma cells." (PMID 33187183, 2020). "We found that ARHI can decrease Ras expression and inbibit the activation of AKT and mTOR, then, promoting autophagy in glioma cells." (PMID 31088402, 2019). "Enforced expression of miR-1229-3p or reduced mTOR expression significantly promoted glioma cell apoptosis, induced G1 phase arrest and inhibited cell proliferation." (PMID 31875034, 2019). "For instance, BRAF 35, EGFR 36, EZH2 37, MET 38 and mTOR 39 have been reported as potential protein targets for glioma treatment." (PMID 31523189, 2019). "The combination of rapamycin with oncolytic VACV JX-594 promoted oncolysis and enhanced viral replication in glioma cells, suggesting a critical role of the mTOR pathway for the effectiveness of OVs." (PMID 31284426, 2019). "Accordingly, mTOR inhibitors reduced ROS levels in glioma cell lines as observed in an exploratory approach." (PMID 31510109, 2019). "It suggested that circPCMTD1 regulates mTOR expression and affects the glioma cell phenotype by competing with miR-224-5p." (PMID 31179240, 2019). "R-2HG produced by mutant IDH in low-grade glioma was shown to activate the mammalian target of rapamycin (mTOR) signaling pathway, which is important for cell growth and metabolism." (PMID 31817761, 2019). "According to our study, over-expression of ARHI can decrease the expression of Ras in glioma cells, thus indirectly suppressing mTOR activity and ultimately initiating autophagy." (PMID 31088402, 2019). "The significantly enriched cancer-related pathways included pathways in cancer, MAPK signaling pathway, mTOR signaling pathway, and glioma." (PMID 31844032, 2019). "In further rescue experiments, transfection with mTOR OV can restore the abilities of glioma cell proliferation, invasion and migration even if hsa_circ_00037251 was knocked down using siRNAs." (PMID 31875034, 2019).
glioma (continued). "Among the various mechanisms through which PTEN/PI3K/Akt/mTOR hyper-activation sustains glioma cells metabolism, autophagy suppression plays a seminal role." (PMID 31387280, 2019). "Since the effects of INK-128 and NVP-Bez235 on human glioma cells have been characterized only marginally, we first assessed their capacity to effectively inhibit mTOR signaling in LNT-229 glioma cells at different concentrations." (PMID 31510109, 2019). "Collectively, these data indicated that triptolide induced G2/M phase arrest, apoptosis, and autophagy via activating the ROS/JNK and blocking the Akt/mTOR signaling pathways in glioma cells." (PMID 31157167, 2019). "Voxtalisib plus temozolomide, an alkylating agent, with or without radiotherapy also displayed a favorable safety profile and moderate amount of PI3K/mTOR pathway inhibition in patients with high-grade glioma." (PMID 31817676, 2019). "Taken together, these results confirmed that XL765 inhibited PI3K/mTOR signaling in our low-grade glioma models." (PMID 31324855, 2019). "It has also been reported that LGG tumors from patients treated with TMZ who present with recurrent gliomas show activation of the PI3K/mTOR pathway, likely as a result of treatment." (PMID 31324855, 2019). "Hyperactivation of downstream phosphatidylinositol 3-kinase (PI3K)/AKT/ mammalian target of rapamycin (mTOR) pathway is a common occurrence of human glioma." (PMID 30857276, 2019). "Our results demonstrate that G0S2 regulates glioma radioresistance through mTOR/S6K/ RNF168/53BP1-regulated DNA repair." (PMID 30953555, 2019). "The BTK inhibitor ibrutinib is a promising new therapeutic strategy for glioma, blocking the proliferation, migration and invasion properties and inducing apoptosis and autophagy of glioma cells, targeting the Akt/mTOR pathway." (PMID 30733667, 2019). "Of note, a decrease in the total protein levels of mTOR was detected in both glioma cells exposed to SRT2183." (PMID 31319814, 2019). "The PTEN/PI3K/Akt/mTOR pathway is aberrantly activated in a variety of human cancers, including gliomas and GBM." (PMID 31387280, 2019). "Downregulation of mTOR was also observed when circPCMTD1 was silenced, while upregulation of mTOR was also observed when circPCMTD1 was overexpressed in glioma cells." (PMID 31179240, 2019). "The phosphoinositide-3-kinase (PI3K)/mammalian target of rapamycin (mTOR) pathway represents an attractive therapeutic target for IDHmut gliomas, but noninvasive indicators of drug target modulation are lacking." (PMID 31324855, 2019). "On the other hand, CD164 downregulation reduces glioma cell proliferation, migration, and tumor invasion via depression of the Akt/mTOR pathway and autophagy induction." (PMID 31387280, 2019). "In pediatric gliomas, for instance, activation of the PI3K/Akt/mTOR pathway has been associated with PTEN promoter methylation, which is also found in >80% of secondary adult GBM cases." (PMID 31007847, 2019). "For instance, miR-451 is upregulated in glioma compared with control brain tissue; furthermore decreased miR-451 expression was associated to a suppressed tumor cell proliferation via CAB39/AMPK/mTOR pathway in two glioma cell lines." (PMID 31921637, 2019). "As previously reported, miR-199a-3p is capable of suppressing the proliferation of glioma cells through the regulation of the AKT/mTOR signaling pathway." (PMID 31386624, 2019). "The mTOR pathway is often altered in gliomas and has led to the development of mTOR inhibitors as a therapeutic approach." (PMID 31795417, 2019). "In this study, we observed that SRT2183 downregulates the phosphorylation levels of AKT as well as mTOR in the tested glioma cells." (PMID 31319814, 2019). "In our study, AKT/mTOR was markedly inhibited by DKGζ knockdown in U251 cells, indicating the interesting role of DKGζ in glioma." (PMID 31523189, 2019).
glioma (continued). "In our study, differences in mTOR inhibitor sensitivity in correlation to mTOR activity and other metabolic treatment combinations were studied using three human in vitro cultured glioma cell lines." (PMID 30574020, 2018). "Based on these, there is a great hope that new or old metabolic inhibitors such as mTOR inhibitors and other metabolism targeting drugs will turn the recent therapy highly effective in patients, especially in gliomas." (PMID 30574020, 2018). "CASC2 was down-regulated in glioma, and overexpression of CASC2 reduced TMZ-induced autophagy via mTOR up-regulation by targetting miR-193a-5p, thus enhancing the sensitivity of glioma cells to TMZ cytotoxicity." (PMID 30266744, 2018). "In vitro proliferation assays, protein expression and metabolite concentration analyses were used to study the effects of mTOR inhibitors, other metabolic treatments and their combinations in glioma cell lines." (PMID 30574020, 2018). "Rapamycin, an inhibitor of the mTOR signaling pathway, promoted malignant glioma cell death and sensitized glioma to combined radiotherapy or temozolomide treatment by autophagic activation along with increased expression of Beclin-1, Atg5 and LC3-II45." (PMID 30302016, 2018). "Temsirolimus, an mTOR inhibitor, has demonstrated drug levels in tissue above those in the plasma of glioma patients, yet in another study negligible CSF drug levels were observed in CNS lymphoma patients." (PMID 29986691, 2018). "Pretreatment with dactolisib resulted in a significant reduction in p-AKT and mTOR protein expression as compared to TMZ+RT treatment in these glioma cells." (PMID 29416647, 2018). "Next, we examined the underlying PLOD3 mechanism in glioma, including EMT markers and the PI3K/AKT/mTOR signaling pathway, which has been reported to play a critical role in regulating angiogenesis in glioma." (PMID 29644003, 2018). "The PI3K/Akt/mTOR pathway is overactive in glioma tumors, resulting in reduced apoptosis and increased tumor proliferation, being frequently implicated in resistance to anticancer therapy." (PMID 30524273, 2018). "CASC2 is negatively downregulated with miR-193a-5p in temozolomide resistant glioma tissues and induce autophagy by controlling mTOR expression to promote drug resistance." (PMID 30693021, 2018). "Targeting β1-integrin/mTOR pathway was also suggested as a therapeutic strategy to overcome chemotherapy resistance to docetaxel for the treatment of gliomas." (PMID 29108253, 2017). "enhanced ERβ expression and sensitized glioma cells to TMZ-induced proliferation inhibition via the PI3K/AKT/mTOR pathway." (PMID 29113424, 2017). "Further studies are needed to elucidate the involvement of mTORC2 in the invasiveness of glioma cells with an activation of the EGFR-PI3K/Akt-mTOR pathway." (PMID 29207533, 2017). "nf1a+/−/nf1b−/− mutants in the p53zdf1/zdf1 background developed brain tumors in 33 weeks, with characteristic markers (sox10/Olig2/Gfap) of diffuse high-grade gliomas and hyperactivation of ERK and mTOR pathways, similar to mouse models and human gliomas." (PMID 28930163, 2017). "A very recent study has suggested that Gab1 is important for activation of PI3K-Akt-mTOR activation in human glioma cells." (PMID 28291820, 2017). "Taken together, our results show that inhibition of the PI3K/mTOR pathway makes adult and pediatric glioma cells more sensitive to radiation." (PMID 28624789, 2017). "Another dual PI3K/mTOR inhibitor, PI-103, an effective monotherapy for glioma, was recently shown to specifically reduce tumor volumes in combination with Neural stem cell delivered s-trail in an orthotopic intracranial xenograft model." (PMID 28423515, 2017).
glioma (continued). "An intense clinical investigation is going on with approximately twenty current clinical studies using mTOR inhibitors for the treatment of gliomas." (PMID 29259984, 2017). "In contrast, CRNDE knockdown suppressed these processes by decreasing p70S6K phosphorylation, suggesting that CRNDE can influence mTOR signaling in glioma." (PMID 28187439, 2017). "HULC silencing suppresses angiogenesis by inhibiting the PI3K/AKT/mTOR signaling pathway in human gliomas." (PMID 28993733, 2017). "CRNDE was found to promote cell growth and invasion through mTOR signaling in glioma, and CRNDE also promoted tumor growth in medulloblastoma." (PMID 29299168, 2017). "The knockdown of mTOR and Bcl‐2 exerted a similar effect as depletion of miR‐497 on reducing both glioma cell lines resistance to TMZ treatment." (PMID 28064447, 2017). "Based on our recent findings and the emerging data about the relation between high mTOR activity and IDH mutation, we also highlight the importance of recently ongoing and future studies in different AMLs, gliomas, and sarcomas." (PMID 28578659, 2017). "Subsequently, preliminary evidence suggested that CRNDE enhances glioma malignancy via stimulation of the mTOR signaling pathway." (PMID 29152149, 2017). "Secondly, we highlight processes (including the Randle Effect, AMPK signaling, mTOR activation, etc.)which are understood to link bio-energetic pathways with oncogenic signals, thereby allowing the glioma cell to achieve a pro-malignant state." (PMID 28491867, 2017). "Our findings shed new light onto the molecular mechanisms of regulation of GBM cell motility by sCPE and display a novel role of sCPE in tumor cell biology by functionally linking it with mTOR signaling, tumor metabolism and glioma cell migration." (PMID 28978054, 2017). "Cyclooxygenase inhibitor indomethacin inhibits proliferation of glioma cells, and has been reported to reduce the activity of the main autophagy repressor mammalian target of rapamycin (mTOR)." (PMID 28243617, 2017). "There is evidence showing that the PI3K/AKT/mTOR cascade has been considered as the predominant downstream pathway of ErbB kinases, promoting radioresistance in various types of cancer including glioma." (PMID 29190914, 2017). "ROS are also able to inhibit LKB1-mediated activation of AMPK, alleviating mTOR inhibition and promoting entry into the cell-cycle and glioma proliferation in vitro." (PMID 28491867, 2017). "The anti-tumour effects of rapalogs, other mTOR inhibitors and elevated mTOR activity have been described previously in many tumours including gliomas, AMLs and chondrosarcomas (where the occurrence of the IDH mutation is remarkable)." (PMID 28578659, 2017). "Silencing Nrf2 inhibited proliferation of glioma cells via AMP-activated protein kinase- (AMPK-) activated mammalian target of rapamycin (mTOR)." (PMID 27547291, 2016). "Investigation of the molecular mechanisms demonstrated that CpG ODN107 + irradiation increased the levels of TLR9 and p-ERK, and decreased the level of p-mTOR in glioma cells." (PMID 27251306, 2016). "MiR-129 induced autophagy through mTOR signaling by targetedly suppressing Notch-1 in glioma cell lines." (PMID 26824182, 2016). "Rapamycin is an allosteric inhibitor of mTOR, which has been shown to dramatically reduce the self-renewal and tumorigenic activity of glioma cells and GSCs." (PMID 27822457, 2016). "It has been shown that the activation of Akt signaling leads to increased proliferation and survival of GBM cells, and Akt/mTOR signaling has been targeted for glioma therapeutics." (PMID 27564106, 2016). "The aberrant PI3K/Akt/mTOR pathway has been shown to contribute to the resistant phenotype of gliomas." (PMID 26830677, 2016). "Genetic mTOR silencing or pharmacological treatment with rapamycin markedly reduced SOX2 levels in glioma cells." (PMID 27822457, 2016). "GSK621 activated AMPK to inhibit mammalian target of rapamycin (mTOR) and downregulate Tetraspanin 8 (Tspan8) in glioma cells." (PMID 27532105, 2016).